MIR1265 (microRNA 1265)
Synonyms: hsa-mir-1265; MIRN1265
Gene: MicroRNA gene on chromosome 10 (14,436,576 to 14,436,661, forward strand). Ensembl gene ENSG00000221371.
Gene Ontology:
Biological process: miRNA-mediated post-transcriptional gene silencing
Cellular component: RISC complex